MTAP (methylthioadenosine phosphorylase)
Diseases named in the same sentence as MTAP in open-access papers (continued):
Sharing a sentence is not in itself a finding about the gene and the disease.
glioblastoma (42 papers, 2009 to 2026). The most malignant astrocytic tumor (WHO grade IV). "For instance, MTAP-deficient tumors have shown improved treatment outcomes in various cancers such as pancreatic cancer and glioblastoma by utilizing PRMT5 as a synthetic lethal target." (PMID 38638876, 2024). "They concluded that there are prominent metabolic differences between in vitro tumor cells and primary human tumor tissue that must be taken into account when developing precise therapeutic strategies for homozygous MTAP‐deficient glioblastomas." (PMID 39711357, 2024). "Mechanistically, suppression of protein arginine methyltransferase 5 (PRMT5) attenuates the expression of RNF168 in methylthioadenosine phosphorylase (MTAP)-deficient glioblastoma cells, contributing to the destabilization of H2AX by SMURF2." (PMID 36694209, 2023). "Low MTAP expression has been linked to a poor prognosis in glioblastoma, gastric cancer, and non-small cell lung cancer, according to earlier research." (PMID 36913304, 2023). "A previous report demonstrated that RNF168 expression is suppressed in methylthioadenosine phosphorylase (MTAP)-deficient glioblastoma cells." (PMID 36771081, 2023). "In a series of glioblastoma cell lines, MTAP-deficient cells grown in 100 μM methionine resulted in the accumulation of high levels of MTA." (PMID 35806160, 2022). "In this article, we review the loss of the 5′-methylthioadenosine phosphorylase (MTAP) gene as a potential therapeutic approach for treating glioblastoma." (PMID 36572880, 2022). "Reduced MTAP expression was associated with a better prognostic in the adult glioblastoma dataset (p < 0.001)." (PMID 32093414, 2020). "Homozygous deletion of 9p21 locus was associated with a reduction of MTAP mRNA expression in the TCGA (The Cancer Genome Atlas) - glioblastoma dataset (p < 0.01)." (PMID 32093414, 2020). "Differently, in glioma cell lines, the loss of MTAP for pediatric glioblastoma (54.8%) was higher than in adult glioblastoma (45.6%) series." (PMID 32093414, 2020). "On the other hand, only 7.4% of the G-CIMP glioblastomas showed loss of MTAP, which is associated with secondary glioblastoma, tumor-harboring mutation of the IDH1 gene, and lesions that progressed from LGG." (PMID 32093414, 2020). "This is in contrast to a number of studies in other cancer types that found deletion and/or mutation of MTAP at high frequency in: glioblastoma (GBM) 151/273 cases; bladder urothelial carcinoma 39/127 cases, and in lung squamous cell carcinoma 46/178 cases." (PMID 26910893, 2016). "Herein we describe the discovery of TNG456, a potent and highly selective MTA-cooperative PRMT5 inhibitor that is brain penetrant in preclinical species and currently in Phase I/II clinical studies for the treatment of advanced or metastatic solid tumors with MTAP loss, with a focus on glioblastoma." (PMID 42150143, 2026). "However, in in vivo experiments, no significant MTA accumulation was found in MTAP‐deficient primary glioblastoma tumors due to the metabolism of MTA by a stroma with normal MTAP expression." (PMID 39711357, 2024). "In this article, we review MTAP with a particular focus on its loss among different tumors and how MTAP loss may be relevant as a therapeutic approach for glioblastoma." (PMID 36572880, 2022). "Besides glioblastoma, MTAP loss is also relevant in multiple other cancers as shown across 32 TCGA PanCancer Atlas Studies, data accessed using cBioPortal." (PMID 36572880, 2022). "MTAP deficient glioblastoma cells showed high levels of DNA damage." (PMID 33816336, 2021). "Overall, we found loss of MTAP expression in 45.95% (233/507) of cases, this being observed in 27.8% (5/18) of diffuse astrocytoma, 50.0% (12/24) of anaplastic astrocytoma, 45.6% (193/423) of adult glioblastoma, and 54.8% (23/42) of pediatric glioblastoma." (PMID 32093414, 2020). "Some studies suggested a higher risk of death among patients with non-small-cell lung cancer or glioblastoma and with MTAP deletions." (PMID 41465382, 2025).
glioblastoma (continued). "For example, in MTAP null glioblastoma, free MTA was predominantly secreted into culture medium, vastly exceeding the measured intracellular pool." (PMID 41339334, 2025). "The safety and efficacy of BMS-986504 are being studied in patients with advanced solid tumors, metastatic NSCLC, and advanced glioblastoma with MTAP deletions." (PMID 41465382, 2025). "Authors showed that MTAP deletion prevalence varied across tumor types and were generally the lowest in gastric cancer (4–14%) and the highest in glioblastoma (26–60%)." (PMID 41465382, 2025). "TNG908 was tested in patients with MTAP-deleted tumors, including glioblastoma, in open-label, dose-escalation and expansion phase I/II study." (PMID 41465382, 2025). "Deletion of CDKN2A/MTAP, one of the most prevalent oncogenic events across all malignancies, occurs frequently in many human tumors, including 53% of glioblastomas and 26% of pancreatic cancers." (PMID 39309689, 2024). "While pemetrexed use in glioblastoma is unexplored, CDKN2A and MTAP loss have emerged as important predictors of pemetrexed benefit in other cancers." (PMID 38187871, 2024). "MTAP deletion is seen in approximately 15% of all solid tumors such as glioblastoma, pleural mesothelioma, and non-small cell lung cancers." (PMID 39409918, 2024). "Homozygous deletion of methylthioadenosine phosphorylase (MTAP) in cancers such as glioblastoma represents a potentially targetable vulnerability." (PMID 34244484, 2021). "Approximately 15% of human cancers are genetically deleted in the MTAP locus, with deletions in specific cancers (eg. glioblastoma) as frequent as 50%43." (PMID 33893330, 2021). "MTAP deficiency can also promote the formation of glioma stem cells (GSC), increase the expression of CD133 and enhance the tumorigenicity of glioblastoma cells, which is related to poor prognosis of patients." (PMID 33816336, 2021). "In the pediatric context, 40 pediatric glioblastoma patients included in the analysis—86.3% (n = 19) in the MTAP-negative group and 77.7% (n = 14) in the MTAP-positive group—died during the total observational time." (PMID 32093414, 2020). "In this community, BMP-7, as a ceRNA driven by MTAP, has been proved to act as a tumor suppressor that repressed proliferation, self-renewal, and tumor initiation of stem-like glioblastoma cells through suppressing epithelial–mesenchymal transition (EMT)." (PMID 31719831, 2019). "Homozygous deletion of MTAP in glioblastoma represents a potentially targetable vulnerability." (PMID 38057821, 2023). "Multiple studies have explored the loss of this gene and have shown its relevance as a therapeutic approach to glioblastoma tumor mitigation; however, other studies show that the loss of MTAP does not have a major impact on the course of the disease." (PMID 36572880, 2022). "Therefore, this discrepancy must be taken into consideration when precision therapies are being developed for glioblastoma with homozygous MTAP deletion." (PMID 36572880, 2022). "The prognostic significance of MTAP deletion has not been previously well characterized, but our results suggest that MTAP deletion may potentially serve as a surrogate marker for CDKN2A deletion in prognostic evaluation of IDHwt glioblastoma patients." (PMID 36380219, 2022). "In addition to accompanying CDKN2A HD, there are also publications indicating that MTAP inactivation contributes to gliomagenesis through epigenetic mechanisms, especially in glioblastomas; thus, MTAP may be a target for treatment." (PMID 38109891, 2024). "Homozygous deletion of MTAP is often observed in glioblastoma (GBM), which represents a potential targetable vulnerability." (PMID 37091983, 2023). "More recent studies suggest that MTA accumulation in MTAP deficient glioblastoma might not be as lethal as anticipated." (PMID 35806160, 2022).
glioblastoma (continued). "Keyword search in PubMed for “MTAP” affords only 455 articles to date (PubMed accessed on May 4, 2022, search for “Methylthioadenosine phosphorylase” resulted in 450 articles, and search for “MTAP” and “glioblastoma” resulted in 23 articles." (PMID 36572880, 2022). "These intragenic deletions included those targeting known tumour suppressors in glioblastoma such as NF1 (17q11.2, n = 2) and RB1 (13q14.2, n = 1), as well as putative novel GBM-associated genes including FAF1 (1p33, n = 2) and MTAP (9p21.3, n = 2)." (PMID 24548782, 2014). "They reported that MTAP can identify CDKN2A status with 88% sensitivity and 98% specificity in astrocytoma Isocitrate dehydrogenase (IDH) mutant tumors, and 89% sensitivity and 100% specificity in glioblastoma, IDH-wildtype." (PMID 39409918, 2024). "In IDHwt glioblastomas, CDKN2A, CDKN2B, and MTAP predict for poor prognosis." (PMID 36380219, 2022). "We further demonstrate that homozygous MTAP-deleted primary glioblastoma tumors do not significantly accumulate MTA in vivo due to metabolism of MTA by MTAP-expressing stroma." (PMID 34244484, 2021). "We found that, in adult glioblastoma, patients exhibiting a lack of MTAP expression had better survival than those presenting MTAP expression (median survival of 9.8±0.86 vs. 6.23±0.70 months, respectively, p = 0.00023 in log-rank test)." (PMID 32093414, 2020). "However, the search for “Methylthioadenosine phosphorylase” and “glioblastoma” resulted in only 12 articles of which three were reviews but notably there was no review article specifically on MTAP to date." (PMID 36572880, 2022). "However, given that the response to PRMT5 inhibitor therapy is partially dependent on molecular contexts such as MTAP deletion or altered splicing as seen in glioblastoma, its mechanism may not be tissue-specific but molecularly defined." (PMID 34680285, 2021).
glioma (29 papers, 2011 to 2026). A benign or malignant brain and spinal cord tumor that arises from glial cells (astrocytes, oligodendrocytes, ependymal cells). "MTAP deficiency leads to epigenetic reprogramming, promotes the formation of glioma stem-like cells, increases PROM1/CD133 expression and tumor incidence, and is associated with poor patient prognosis." (PMID 40761256, 2025). "PRMT5 and MAT2A show promise as a combined target in gliomas where 5′-methylthioadenosine phosphorylase (MTAP) deficiency accounts for approximately 30%." (PMID 40450009, 2025). "Some studies have pointed out that the deletion of MTAP in different grades of glioma is different, and MTAP expression loss in the high‐grade glioma subgroup was almost twofold greater than in the lower‐grade glioma subgroup." (PMID 39711357, 2024). "The results showed that MTAP‐deficient glioma tissues were surrounded by a large number of microglia with normal MTAP expression." (PMID 39711357, 2024). "In order to further verify this conclusion, we attempted to determine the antitumor activity of MRTX1719 using an orthotopic in vivo model, but it is failed due to the specificity of MTAP‐deficient gliomas." (PMID 39711357, 2024). "To mimic the in vivo environment, we used MTAP‐deficient glioma cells co‐cultured with microglia and neurons." (PMID 39711357, 2024). "Then, we simulated the inhibitory effect of PRMT5/MTA inhibitor on GBMs by in vitro and in vivo experiments in which MTAP‐deficient glioma cells coexisted with microglia and neurons with normal MTAP expression." (PMID 39711357, 2024). "Results of Western blot and immunofluorescence suggested that normal MTAP‐expressing tissues in the mixed‐inoculated tumor tissues were present in close proximity to the MTAP‐deficient tumor cells, as compared to MTAP‐deficient glioma cells inoculated alone." (PMID 39711357, 2024). "Then, in vivo and in vitro models of MTAP‐deficient gliomas coexisting with neurons or glial cells were constructed for evaluating the effectiveness of the anti‐tumor effects of MRTX1719 in this setting." (PMID 39711357, 2024). "MRTX1719 inhibits proliferation significantly in MTAP‐deficient gliomas compared to MTAP‐expressing normal gliomas." (PMID 39711357, 2024). "MTAP loss has been commonly observed in multiple malignancies, including gliomas, pancreatic cancer, mesothelioma and non-small cell lung cancer (NSCLC)." (PMID 37091983, 2023). "MTAP loss leads to hypomethylation of PROM1/CD133-related stemness networks to mediate glioma stem-like cell formation, providing a promising therapeutic opportunity for GBM." (PMID 37091983, 2023). "Further research is required to find additional details and also study the impact of MTAP loss in the context of pediatric glioma." (PMID 36572880, 2022). "In gliomas, loss of MTAP expression is associated with 9p21 locus deletion and as shown based on the data in cBioPortal it is often co-deleted with CDKN2A in many cancers." (PMID 36572880, 2022). "The purpose of this study was to characterize the MTAP expression profile in a series of gliomas and to associate it with patients’ clinicopathological features." (PMID 32093414, 2020). "When we stratified the samples by grade, the loss of MTAP expression in the high-grade glioma subgroup was almost two-fold greater (46.6%, 228/489) than in the low-grade glioma subgroup (27.8%; 5/18)." (PMID 32093414, 2020). "We found loss of MTAP expression greater than 50% in almost all subtypes analyzed, except for the glioma CpG island methylator phenotype (G-CIMP)." (PMID 32093414, 2020). "Initially, using an in silico approach, we showed that 48% (168/350) of gliomas had 9p21 locus deleted, and this deletion was directly associated with reduced MTAP expression." (PMID 32093414, 2020). "In glioma cell lines, we observed loss of MTAP in high-grade glioma cells, contrasting with low-grade glioma (40% vs. 0%)." (PMID 32093414, 2020).
glioma (continued). "In summary, the present work showed that loss of MTAP expression is a frequent event in high-grade gliomas." (PMID 32093414, 2020). "In gliomas, a recent study showed compelling data that MTAP loss is responsible for epigenetic remodeling and stemness properties." (PMID 32093414, 2020). "Herein, we extended the immunohistochemistry analysis to a large set of diffuse infiltrative astrocytomas and observed association between loss of MTAP expression and malignancy grade of gliomas." (PMID 32093414, 2020). "Previous studies have reported gliomas are frequently associated with abnormalities in chromosome 9 and the MTAP locus is located at 9p21.3." (PMID 29164057, 2017). "The deficiency of MTAP has been reported in both solid tumors and hematologic malignancies, specifically glioma, leukemia, non-small cell lung cancer, hepatocellular carcinoma, gastric carcinoma, and melanoma." (PMID 29164057, 2017). "This enzyme is expressed in all normal human tissues, but MTAP protein deficiency or MTAP gene deletion have been previously found in several tumors, including gliomas." (PMID 23029397, 2012). "PRMT5 activity is inhibited in MTAP-deficient glioma cells, which, in turn, downregulates the expression of E3 ubiquitin ligase SMURF2, leading to decreased stability of downstream histone H2AX and ultimately resulting in the genomic instability of tumor cells." (PMID 40450009, 2025). "We first analyzed whether there were MTAP‐expressing normal intracerebral cells around MTAP‐deficient glioma tissues by paraffin‐embedded tissue microarray of human glioma specimens." (PMID 39711357, 2024). "Large amounts of MTA produced by MTAP‐deficient gliomas may be taken up and metabolized by surrounding tissues with normal MTAP expression." (PMID 39711357, 2024). "Different studies have shown varying results for MTAP loss in pediatric glioma." (PMID 36572880, 2022). "Moreover, the CDKN2A/MTAP deletion is mostly observed in higher grade glioma and hence tumors at early stage cannot be treated by solely targeting MTAP loss." (PMID 36572880, 2022). "Moreover, by using a genome edition gain- or loss-of MTAP-function approach in glioma cell lines, we explored MTAP biological impact on gliomas." (PMID 32093414, 2020). "In addition, the loss of MTAP expression was markedly high in high-grade gliomas (46.6% of cases) determined by IHC and Western blotting (40% of evaluated cell lines)." (PMID 32093414, 2020). "Therefore, the aim of this study was to characterize the MTAP protein expression profile in a large series of glioma and to associate it with the patients’ clinicopathological features." (PMID 32093414, 2020). "To investigate whether the loss of MTAP could affect glioma cell motility and invasiveness, we used the transwell cell migration assay." (PMID 32093414, 2020). "Some studies have shown that co-deletion of CDKN2A and MTAP could be used as markers for glioma stratification, and the deletion of CDKN2A was associated with the expression of CDK4/6 in various tumors." (PMID 31719831, 2019). "MTAP deficiency has been reported in both liquid and solid tumors, including gliomas." (PMID 29164057, 2017). "Interestingly, a deletion resulting in a fusion protein between MTAP and tumor suppressor gene encoding p15INK5B was reported in a glioma xenograft as well as other malignant cell lines." (PMID 22032724, 2011). "Overall, we found loss of MTAP mRNA expression in 33.3% (6/18) of the cell lines evaluated, particularly in 36.3% (4/11) of established cell lines, with 25% (1/4) for pediatric and 42.8% (3/7) for adult glioma cell lines, and 29% (2/7) of patient-derived glioma cell lines." (PMID 32093414, 2020). "After constructing glioma organoids from patients and verifying their parental characteristics, MTAP expression was tested using immunofluorescence experiments." (PMID 40450009, 2025).